RNA5SP150 (RNA, 5S ribosomal pseudogene 150)
Synonyms: RN5S150
Gene: Ribosomal RNA gene on chromosome 3 (181,822,872 to 181,822,990, reverse strand). Ensembl gene ENSG00000199839.
Homologues: Orthologues: chimpanzee 5S_rRNA (96% identical), macaque 5S_rRNA (94% identical), guinea pig 5S_rRNA (78% identical), guinea pig 5S_rRNA (76% identical). Paralogues in human: RNA5S1 (97% identical), RNA5S10 (97% identical), RNA5S11 (97% identical), RNA5S12 (97% identical), RNA5S13 (97% identical), RNA5S14 (97% identical), RNA5S15 (97% identical), RNA5S16 (97% identical), RNA5S17 (97% identical), RNA5S2 (97% identical), RNA5S3 (97% identical), RNA5S4 (97% identical), and 26 more.